MIR129-1 (microRNA 129-1)
Synonyms: hsa-mir-129-1; MIR-129b; MIRN129-1; mir-129-1
Gene: MicroRNA gene on chromosome 7 (128,207,872 to 128,207,943, forward strand). Ensembl gene ENSG00000207705.
Gene Ontology:
Biological process: miRNA-mediated post-transcriptional gene silencing
Cellular component: RISC complex
Homologues: Orthologues: chimpanzee ptr-mir-129-1 (100% identical), pig ssc-mir-129b (99% identical), guinea pig MIR129-1 (94% identical), mouse Mir129-1 (92% identical), rat Mir129-1 (92% identical), rabbit MIR129-1 (90% identical), zebrafish dre-mir-129-1 (90% identical), zebrafish mir129-1b (90% identical). Paralogues in human: MIR129-2 (83% identical).